KRAS (KRas proto-oncogene, GTPase)
Diseases named in the same sentence as KRAS in open-access papers (continued):
Sharing a sentence is not in itself a finding about the gene and the disease.
colon carcinoma (continued). "The careful comparison of KRAS-dependent and KRAS-independent colon cancers led to the identification of MAP3K7, encoding the TGF-β-activated kinase (TAK1), as a driver of cell survival of KRAS-mutated-dependent, APC-deficient cells." (PMID 29652830, 2018). "Numerous cell lines from KRAS mutated colon cancers have been isolated and analyzed for their dependency for growth/survival from mutated KRAS, showing that about 50% of these lines are KRAS-dependent." (PMID 29652830, 2018). "In the KRASWT cell line of HT-29, Caco-2 and A549 cell proliferation was approximately 80%, which indicated that GSC is more effective on KRAS-mutated colon cancer." (PMID 30577618, 2018). "The aim of this study was to investigate the influence of BRAF and KRAS mutation status on the association between aspirin use and overall survival after colon cancer diagnosis." (PMID 28125730, 2017). "To further investigate the effects of Episilvestrol in KRAS/BRAF mutated colon cancer, we selected four more cell lines, HT29 (BRAF600E), VACO432 (BRAF600E), LOVO (KRASG13D and SW480 (KRASG12V)." (PMID 28030835, 2017). "In a recent study, CDK1 is reported as a synthetic lethality target for KRAS mutation in colon cancer." (PMID 28486948, 2017). "For instance, in colon cancer cells, the deprivation of glucose or subcutaneous space in mice grown in a harsh environment caused selective stress on KRAS mutations." (PMID 28749413, 2017). "This is consistent with previous findings showing that the KRAS G13 mutation was an independent prognostic factor for poor metastasis-free survival in colon cancer compared with either wild-type KRAS or G12 mutation." (PMID 28430579, 2017). "A BRAF mutation was found in 17% (102/599) and a KRAS mutation was observed in 35% of colon tumors (212/599), in accordance with previous studies." (PMID 28125730, 2017). "This was largely restricted to KRAS wild-type cultures and was strongly associated with deficient mismatch repair (dMMR) in human colon cancer." (PMID 28300842, 2017). "Several studies have tried to overcome the cetuximab resistance of KRAS-mutated colon cancers, including those using microRNA, L-ascorbic acid, lauric acid, cisplatin, dasatinib, and simvastatin." (PMID 28800074, 2017). "When cetuximab and PBR extract were combined, enhanced antitumor activity (as assessed by cell viability and clonogenic properties) in G12V KRAS mutant colon cancer cells was observed, which was caused by apoptosis." (PMID 28800074, 2017). "Molecular studies revealed the presence of KRAS G12S mutation in the primary colon cancer tissue specimen." (PMID 27906677, 2017). "In this study, we prepared Phellinuslinteus on germinated brown rice (PBR) extracts to increase the sensitivity of KRAS-mutated colon cancers to cetuximab." (PMID 28800074, 2017). "KRAS mutations are more relevant to patients with lung, pancreatic, and colon cancers and leukaemias." (PMID 28508873, 2017). "In this study, we prepared Phellinuslinteus grown on germinated brown rice (PBR) extracts to increase the sensitivity of KRAS-mutated colon cancers to cetuximab." (PMID 28800074, 2017). "In conclusion, PBR increased the sensitivity of KRAS-mutated colon cancer cells to cetuximab, which indicates the potential use of PBR as a medical food against colon cancer." (PMID 28800074, 2017). "Nevertheless, this subject is under debate with other studies linking sub-clonality to early disease stage for BRAF mutation in thyroid cancer and KRAS mutation in pancreatic and colon cancer." (PMID 28501852, 2017). "Unfortunately, it is estimated that 30–40% of colon cancer patients have a KRAS mutation, giving them very few therapeutic options." (PMID 28800074, 2017). "Among of them, oncogenic RAS mutation is the most frequent mutation in colon cancers, and KRAS is the most commonly mutated isoform of RAS." (PMID 28165459, 2017).
colon carcinoma (continued). "This pilot study applied word frequency analysis and a naive Bayes classifier on free-text radiology reports to extract distinguishing imaging descriptors of wild-type colon cancer patients and those with KRAS mutations." (PMID 28869500, 2017). "Next, we included colon cancer models able to associate the activity to the KRAS- and BRAF mutation status, established to have predictive and/or prognostic importance in this tumor type." (PMID 28415818, 2017). "Approximately 30–40% of patients with colon cancer have a KRAS mutation, and they cannot benefit from cetuximab therapy." (PMID 28800074, 2017). "In subsequent studies, we found that among wild-type KRAS colon cancer cells, those harbouring active mutations in BRAF were even more resistant to AUY922-induced apoptosis than cells with wild-type BRAF." (PMID 27391062, 2016). "Additional driver mutations such as oncogenic KRAS occur in the context of enlarging colon adenomas to enhance colon cancer initiation." (PMID 26744320, 2016). "Nearly half of all colon cancers contain KRAS/BRAF mutations and the numbers are higher in bigger or more advanced tumors." (PMID 27351224, 2016). "Mutations in APC and KRAS were frequently co-occurring in this series of 60 MSS colon cancer samples (Fisher-Exact: p = 0.002)." (PMID 27729614, 2016). "In this study, we performed deep RNA-Seq analysis of rRNA-depleted total RNA libraries to characterize circRNA expression in three isogenically-matched human colon cancer cell lines that differ only in the mutation status of the KRAS oncogene." (PMID 27892494, 2016). "DNA extracted from tissues collected from 182 colon cancer patients was used to check the existence of KRAS mutation." (PMID 25936694, 2015). "The presence of a KRAS mutation is predictive for resistance to anti-EFGR monoclonal antibodies (mAbs) in advanced colon cancer." (PMID 25929517, 2015). "Colon cancer cells with oncogenic KRAS mutation and expressing both HIF-1α and HIF-2α were shown to maximize ATP production and minimize ROS generation, probably through the induction of enzymes important for mitochondrial cardiolipin synthesis." (PMID 25590810, 2015). "In this aspect, previous studies demonstrated the effectiveness of TAK1 inhibition or deficiency in skin cancer, multiple lymphoma, KRAS-dependent colon cancers, breast cancer and cervical cancer." (PMID 26381601, 2015). "Having established that IQc compounds repress mutated KRAS expression in KRAS-dependent colon cancer cells, we then investigated if this would translate into induced cancer cell death by apoptosis." (PMID 25853628, 2015). "This study aims to characterize colon cancer with regard to KRAS, BRAF, and PIK3CA mutations, microsatellite instability (MSI), and average DNA copy number, in connection with tumour dissemination and recurrence in patients with colon cancer." (PMID 25884297, 2015). "Erlotinib resistance in BRAF- and KRAS-mutated colon cancers is clearly reflected in their Raman difference spectra." (PMID 26168967, 2015). "Using an isogenic system, we confirmed that the introduction of a KRAS G13D or G12V mutation in the KRAS WT SW48 colon cancer cell line conferred resistance to ixazomib in vivo." (PMID 26709701, 2015). "Our data in colon cancer showed that the majority of mutations identified were shared between a primary tumor and its cognate paired metastatic lesion, including KRAS, APC, and PIK3CA which are commonly tested mutations in our patients." (PMID 25974029, 2015). "It has been reported that colon cancer patients with KRAS and BRAF mutations that lie downstream of epidermal growth factor receptor (EGFR) acquire resistance against therapy with anti-EGFR antibodies, cetuximab and panitumumab." (PMID 25936694, 2015).
colon carcinoma (continued). "Activating KRAS mutations in CRC tumor samples are an early event in the progression of colon carcinoma and the only predictive molecular marker useful for treatment decision as EGFR directed therapy is ineffective in the context of concomitant KRAS mutation." (PMID 24943349, 2014). "This suggests that trastuzumab is a possible treatment option for patients with colon cancer and KRAS mutation." (PMID 24668895, 2014). "In this study we find that GNAS mutations associate with a distinct subclass of colon cancers that is typified by location in the proximal colon, by having coincident KRAS or BRAF mutation, and by association with villous morphology." (PMID 24498230, 2014). "KRAS mutations in colon cancers have been associated with a poorer survival and increased tumor aggressiveness." (PMID 25713627, 2014). "Here we show that GNAS mutant colon tumors harbor recurrent KRAS or BRAF mutations, target the anatomic proximal “right-sided” colon, and exhibit a villous morphology." (PMID 24498230, 2014). "We evaluated the effect of c-Met targeting alone or c-Met targeting in combination with irradiation or a variety of anticancer drugs on malignant colon cancer cell lines harboring a KRAS mutation." (PMID 25427200, 2014). "A sub group of colon cancer patients (~40%) harbor mutations in the KRAS oncogene, and are precluded from receiving anti-EGFR targeted therapies." (PMID 24798549, 2014). "The enhancement of c-Met inhibition on the anti-proliferative effects of 5-FU and Taxol was also observed in another colon cancer cell lines HCT-116 which also containing KRAS mutation." (PMID 25427200, 2014). "Taken together, these data indicate that GNAS mutant colon tumors commonly have synchronous mutations in KRAS or BRAF, are right-sided in location, and are associated with a villous morphology." (PMID 24498230, 2014). "Contrary to resistance against EGFR and ERBB2 targeting, the genetic inhibition of ERBB3 results in anti-tumorigenic in HCT116 colon cancer cells harboring constitutively active KRAS and PIK3CA mutations." (PMID 24970817, 2014). "In clinical specimens, approximately 30–50% of colon cancers were reported to harbor KRAS mutations." (PMID 24265711, 2013). "KRAS: The important therapeutic KRAS mutation in colon cancer was detected in ID.3 and ID.6 (exon 2 aa12), two EGFR wildtype samples." (PMID 23922754, 2013). "We show increased expression of a mutated KRAS codon 61 allele along with tumor progression in a colon cancer sample." (PMID 24280411, 2013). "Recent evidence suggests that a biopsy should be taken immediately prior to treatment initiation to assure KRAS is wild-type as colon cancer patients can evolve KRAS mutations during cetuximab treatment that causes resistance." (PMID 23555026, 2013). "According to some series, the presence of mutated KRAS is predictive of lung metastases in patients with primary colon tumors." (PMID 29147353, 2013). "We examined five melanoma lines, three of which were BRAF- and two NRAS-mutated, and four colon carcinoma lines, of which three were KRAS- and one BRAF-mutated." (PMID 22869096, 2012). "In conclusion, this study confirms and extends our previous data showing that concomitant inhibition of two commonly mutated pathways (Wnt and KRAS) leads to superior antitumor effects in colon cancer cells that carry those mutations." (PMID 23227266, 2012). "Dilutions of DNA extracted from the KRAS mutant HCT116 human colon cancer cell line showed that the KRAS G13D mutation was reproducibly detectable by the OncoCarta v1.0 panel at DNA concentrations as low as 40 ng/ml." (PMID 23144797, 2012). "The tumor types of these responders were estrogen receptor positive breast cancer, cervical cancer and KRAS-mutant colon cancer, and PIK3CA mutations were detected in all three cases (E542K/V, E545K and R88Q respectively)." (PMID 23232172, 2012).
colon carcinoma (continued). "In conclusion, our data suggested that KRAS mutation is a predictor of oxaliplatin sensitivity in colon cancer cells by ERCC1 downregulation." (PMID 23209813, 2012). "Overall, our findings suggest that KRAS mutation is a predictor of oxaliplatin sensitivity in colon cancer cells by the mechanism of ERCC1 downregulation." (PMID 23209813, 2012). "The clinical response observed in the colon cancer patient with coexistent KRAS and PIK3CA mutations contrasts with the preclinical finding in which such coexpression generally conferred resistance to BYL719." (PMID 23232172, 2012). "KRAS mutations in colon cancers have been associated with poorer survival and increased tumor aggressiveness." (PMID 23202889, 2012). "NRAS is the most commonly mutated Ras family member in melanoma, KRAS is predominantly mutated in colon cancer, while BRAF mutations are found in either malignancy." (PMID 22869096, 2012). "Our study shows that KRAS mutation is a predictor of oxaliplatin sensitivity in colon cancer cells by ERCC1 downregulation." (PMID 23209813, 2012). "KRAS mutations have been found in about 35% of colon carcinomas that mainly occur at codons 12, 13 and 61, resulting in a constitutively active form of KRAS GTPase." (PMID 21943101, 2011). "KRAS mutant tumours did not demonstrate mutations in EGFR consistent with previous reports in both NSCLC and colon carcinoma which suggest that KRAS mutations predict resistance to EGFR antagonists." (PMID 21385341, 2011). "In this context, it is interesting to note that the loss of IFI16 expression in human colon cancer cell lines is associated with KRAS mutations." (PMID 21573174, 2011). "Our results thus identify FGFR signals as major determinants of the MEK/ERK cascade activity in SW480 colon cancer cells, even in the presence of an oncogenic KRAS mutation." (PMID 21853123, 2011). "SW480 colon cancer cells contain a well-characterized set of mutations, including an activating KRAS (G12V) mutation." (PMID 21853123, 2011). "When considering the MSI-H carcinomas of the combined series, KRAS exon 2 mutations were detected in five (19%) colon carcinomas located proximally to the sigmoid and in four (25%) rectal/sigmoid carcinomas." (PMID 20979647, 2010). "Conversely, two large collaborative studies, the RASCAL trials, have reported an increased risk of recurrence and death in patients with colon cancer and KRAS mutation." (PMID 20842128, 2010). "Our previous studies demonstrated that mutant KRAS alleles can interact with hypoxia to induce vascular endothelial growth factor (VEGF) in colon cancer." (PMID 20532039, 2010). "We sought to determine the role of K-ras in the hypoxic micro-environment in colon cancer, a tumor type that frequently harbors KRAS mutations." (PMID 20532039, 2010). "When colon tumours and rectal tumours were analysed separately, the presence of a KRAS mutation was associated with a worse DFS for colon cancers and a worse OS for rectal tumours in univariate analysis." (PMID 20959826, 2010). "In colon cancer, previous studies have demonstrated a synergistic interaction between KRAS mutations and hypoxia in the regulation of multiple genes including VEGF." (PMID 20532039, 2010). "In general, KRAS mutations are associated with CIMP-low (also annotated CIMP2) colon tumors, in which increased levels of aberrant methylation can be detected to some extent, but at lower levels than in the CIMP-high tumors." (PMID 20444249, 2010). "In HCT116, a colon cancer line, that carries a mutant KRAS allele, we find that interfering with the RAF effector axis at the level of RAF (BRAF and CRAF) and MEK (MEK1 and MEK2) was effective in delaying tumor growth." (PMID 19492075, 2009). "We report the experiences from our first 136 treatment-predictive KRAS tests and herein report significant differences in mutation frequencies in colon cancer and rectal cancer and coexisting KRAS mutations in a subset of the tumors." (PMID 19832985, 2009).
colon carcinoma (continued). "KRAS mutations were significantly more often found in rectal cancer (21/38, 55%) than in colon cancer (32/98, 33%) (P = 0.02)." (PMID 19832985, 2009). "KRAS mutations, however, significantly correlated with tumor location with mutations found in 32/98 (33%) colon cancers and 21/38 (55%) rectal cancers (P = 0.02; Chi2-test)." (PMID 19832985, 2009). "This differential impact of MEK1 and MEK2 on cell proliferation was observed in three different colon carcinoma cell lines (bearing activating mutations in either KRAS or BRAF), as well as in the breast adenocarcinoma cell line MDA-MB-231." (PMID 19014680, 2008). "We specifically chose the human colon carcinoma cell lines SW480 (which harbors a KRAS mutation like HCT116) and HT-29 (harboring a BRAF mutation)." (PMID 19014680, 2008). "The plasmacytoma cell line RPMI8226 has a heterozygous 35G > C (G12A) KRAS mutation and the colon cancer cell line HCT116 has a heterozygous 38G > A (G13D) mutation." (PMID 17184525, 2006). "Therefore, we developed an SGE-based system for evaluating KRAS mutations in diploid HCT 116 colon carcinoma cells." (PMID 42042001, 2026). "In a study on the colon cancer, researchers found that KRAS mutations can activate the transcription factor TFCP2, which in turn upregulates the expression of adipogenic factors BMP4 and WNT5B, ultimately inducing CAFs to transform into a special subtype rich in lipids." (PMID 41469334, 2026). "Some studies have reported that suppressing or inhibiting α3β1 in colon carcinoma cells reduces their proliferation, invasion and/or migration, and activated KRAS has been linked to increased α3β1 expression in colon carcinoma cells, suggesting cancer-supportive roles for this integrin." (PMID 39941740, 2025). "In addition, the reduction found in KRAS (an oncogene that is mutated in colon cancer) indicates an inhibition of the signaling pathways that favor cell survival and proliferation." (PMID 39860103, 2025). "Indeed, Grunt and colleagues found co-expression patterns of the stem cell markers CD133 and CD26 on KRAS-mutated HC116 colon cancer cells, showing that the co-expression of these markers enhances long-term growth and increased resistance to anticancer agents." (PMID 41426321, 2025). "Higher frequencies of KRAS mutations have also been observed in colon cancer." (PMID 39699266, 2025). "In a retrospective study evaluating the effectiveness of cetuximab added to FOLFOX treatment in adjuvant therapy in patients diagnosed with stage III colon cancer, it was shown that while KRAS mutation was a poor prognostic marker in MSS tumors, it was not a prognostic marker in MSI tumors." (PMID 40142219, 2025). "In addition to these observations, a key research study highlighted an upregulation of CD147 expression on the surface of pancreatic, lung, and colon tumor cell lines harboring KRAS gene mutations compared to KRAS wild‐type cells." (PMID 40727998, 2025). "Even the efficacies of molecular-targeted therapies, however, may differ among tumor types, such as reduced efficacy of BRAF- or KRAS-targeted therapy in colon cancer, possibly because of differences in the biology underlying the respective tumor development." (PMID 40726246, 2025). "The remaining patients were patients with right or left colon tumors and we compared the overall survival (OS), molecular mutations (KRAS, NRAS, BRAF, MSI status), and clinicopathological features of our patients with transverse colon tumors with these patients." (PMID 39629291, 2024). "Similar results have been demonstrated in primary colon cancers, showing that the CT based-radiomics signature was significantly associated with KRAS/NRAS/BRAF mutations and this approach may be useful for analysis of tumor genotype." (PMID 39329997, 2024).